AHR (aryl hydrocarbon receptor)
Diseases named in the same sentence as AHR in open-access papers (continued):
Sharing a sentence is not in itself a finding about the gene and the disease.
steatosis (41 papers, 2011 to 2026). Increased lipid within the cytoplasm of cells. "Inhibition of AhR signaling has been linked to disrupted redox balance in the liver, resulting in increased oxidative stress, apoptosis, steatosis, and inflammation." (PMID 40381698, 2025). "DLPCBs activate the aryl hydrocarbon receptor (AhR) and peroxisome proliferator-activated alpha and gamma receptors (PPARα/γ), exerting a multimodal effect on lipid accumulation and causing steatosis by disrupting hepatic lipid metabolism." (PMID 38276306, 2024). "DLPCBs activate the aryl hydrocarbon receptor (AhR) and peroxisome proliferator-activated receptors alpha and gamma (PPARα/γ), exerting a multimodal effect on lipid accumulation and causing steatosis by disrupting liver lipid metabolism." (PMID 37033031, 2023). "Hepatocyte-specific AhR ablation attenuates steatosis, which is associated with recovery of phospho-/sphingo-lipids content." (PMID 36241614, 2022). "Regardless, the collective results of these studies point to the possibility that HFD acts through AHR to cause obesity and steatosis, potentially through alteration in production of a metabolite (or metabolites) that acts as an AHR ligand." (PMID 32730300, 2020). "Our report extends those findings by showing that PARP is also involved in steatosis caused by activation of the AhR by toxic chemicals such as dioxin, demonstrating a new role for PARP activity in environmental toxicology." (PMID 28536482, 2017). "In addition, indole (X) also activates AhR and can alleviate hepatitis and steatosis associated with MASLD." (PMID 40243472, 2025). "Moreover, these AHR-deficient mice were protected from high-fat diet-induced steatosis, obesity, and inflammation." (PMID 38932276, 2024). "Interestingly, they identified CD36 as a new AHR target and linked steatosis-promoting AHR activation to increased expression of CD36 and lipid uptake into liver cells via CD36." (PMID 34075438, 2021). "AhR plays a major role in stimulating cytokine transcription and AhR deficient mice display an abnormal liver phenotype from birth, with microvesicular steatosis, alterations in extramedullary hematopoiesis (Schmidt, Su, Reddy, Simon, & Bradfield, 1996) and fibrosis." (PMID 32951289, 2020). "Results from this study suggest that statins, which are amongst the most prescribed pharmaceuticals, may protect from AHR-mediated steatosis, but alter glycogen metabolism and increase the risk of TCDD-elicited liver damage in a sex-specific manner." (PMID 31676775, 2019). "Furthermore, results from this mouse experiment suggest that individuals who take statins may be protected from AHR-mediated steatosis, but are at greater risk for TCDD-elicited liver injury and alterations in glycogen metabolism in a sex-specific manner." (PMID 31676775, 2019). "The most developed adverse outcome pathways arefor AhR and ER, whereby their activation has been connected to earlymortality, several cancers, preeclampsia, cognitive decline, liverfibrosis and steatosis, and reproductive dysfunction." (PMID 39839249, 2025). "HepaRG cells are a useful model for studying hepatic steatosis in vitro, as they express important steatosis-related nuclear receptors such as AhR, LXR, PXP, and CAR, as well as exhibit lipid accumulation when treated with known steatotic chemicals." (PMID 40295322, 2025). "Conversely, treatment with endogenous AhR agonists, (e.g., cinnabarinic acid, indole, and indole-3 acetic acid), attenuated steatosis." (PMID 38791241, 2024). "The fatty acid translocase CD36 was recognized as a newly discovered transcriptional target gene of AhR, responsible for mediating the development of steatosis." (PMID 38067179, 2023). "In another study, constitutively activated human AhR transgenic mice subjected to high-fat diet containing 60 kcal% fat for 12 weeks displayed exacerbated steatosis." (PMID 37284280, 2023).
steatosis (continued). "Use of constitutively activated AhR models and exogenous agonists provided evidence towards exacerbated steatosis, fibrosis and other hallmarks of NAFLD." (PMID 37284280, 2023). "The CA-induced AhR-mediated Stc2 induction is thus protective against steatosis, inflammation and liver injury observed in NAFLD." (PMID 37284280, 2023). "In mice with constitutively activated human AhR given a WD, the level of steatosis was higher than in controls." (PMID 37664863, 2023). "Activation of AhR showed decreased body mass and resulted in the induction of spontaneous steatosis characterized by an accumulation of liver triglycerides but not cholesterol." (PMID 37284280, 2023). "Activation of steatosis-relevant NRs was investigated, revealing interactions of the test compounds especially with the NRs AHR, CAR and PXR." (PMID 33575850, 2021). "Adenoviral-mediated expression of AhR in obese mice increases PC levels and exacerbates steatosis, effects that are blunted by SHP co-expression or Pemt downregulation." (PMID 29416063, 2018). "Macroscopic evaluation identified small lesions (upper left) with steatosis in most AhR+/+ mice despite some animals having larger size tumors (upper right)." (PMID 28874739, 2017). "Several studies have shown that dysregulation of AHR in hepatocytes leads to steatosis and aberrant cholesterol metabolism, and increased expression of AHR and its binding partner, ARNT, has been noted in hepatocellular carcinoma (HCC)." (PMID 27283490, 2017). "The AhR’s role in the liver is complex: Ligand II activation may exacerbate steatosis and inflammation, while ligand I induces fatty acid oxidation and improves fatty liver." (PMID 40871736, 2025). "Since AHR agonists can induce oxidative stress in the liver, the increased ratio of micro-/macrosteatosis by C2 may indicate that the transition from steatosis to steatohepatitis could be accelerated in these mice." (PMID 40687891, 2025). "Our results are consistent with these mechanisms: TCDD injection significantly increased hepatic and serum TG levels and lipid droplet formation in WT mice, while reducing mitochondrial OCR, suggesting impaired fatty acid utilization leading to steatosis under AhR activation." (PMID 40943373, 2025). "Furthermore, studies employing transgenic mice with constitutively active human AHR exposed to a high-fat diet exhibited exacerbated steatosis, highlighting a potential link between AHR and hepatic fat accumulation." (PMID 38932276, 2024). "However, liver-specific AhR knockout in mice resulted in severe hepatic lipotoxicity, demonstrated by severe steatosis, inflammation and injury in the livers of KO mice." (PMID 38067179, 2023). "However, stimulation of AhR with indole propionic acid, which shares some of the anti-inflammatory activity of indolines, but at higher concentrations, alleviated steatosis in mice on a WD." (PMID 37664863, 2023). "Moreover, the outcomes of our RNA-seq analyses corroborated the functional roles of AhR and autophagy in hepatocytes in steatosis progression leading to liver dysfunction." (PMID 36241614, 2022). "Accordingly, the pro-steatotic effect of AHR via CYP1A1 activation had been further linked to estrogen metabolism, as estrogen degradation by CYP1A1 diminished the known protective effect of 17β-estradiol (E2) on steatosis." (PMID 34075438, 2021). "Overall, treatment with B. bifidum alone could improve hepatic inflammation and steatosis via AHR." (PMID 38299316, 2024). "Therefore, it can be speculated that both A. muciniphila abundance and microbiota-dependent AHR signaling may contribute to the pathogenesis of the liver inflammation and steatosis of mice induced by NAS consumption through gut-liver interaction." (PMID 33622853, 2021).
steatosis (continued). "Functional annotation analysis of differentially regulated genes associated with AhR enrichment identified overrepresented processes related to fatty acid and lipid metabolism and transport, and xenobiotic metabolism, which are consistent with TCDD-elicited steatosis in the mouse liver." (PMID 21762485, 2011). "Additionally, mitochondrial dysfunction, Aryl Hydrocarbon Receptor (AhR) inhibition, and increased oxidative stress are other MIEs and/or KEs that have been widely explored and modeled, as they can lead to various toxic effects beyond cardiotoxicity, such as steatosis and cholestasis." (PMID 40883848, 2025). "Mice with liver-specific knock-out AHR exhibited enhanced DNL activity, severe hepatic steatosis, inflammation and injury, while activating hepatic AHR by 5-HIAA can alleviate the pathogenesis of T2D." (PMID 39426289, 2024). "The persistent environmental aryl hydrocarbon receptor agonist and hepatotoxin TCDD (2,3,7,8-tetrachlorodibenzo-p-dioxin) induces hepatic lipid accumulation (steatosis), inflammation (steatohepatitis) and fibrosis." (PMID 36711947, 2023). "Given our recovery of Akkermansia organisms, the colonic AHR level, and the number of goblet cells in the metformin or FOS intervention mice, we next assessed hepatic inflammation and steatosis in sucralose-treated mice." (PMID 33622853, 2021). "Collectively, these results demonstrate persistent AhR activation disrupts hepatic OCM metabolism at the transcript, protein and metabolite levels within context of TCDD-elicited progression of steatosis to steatohepatitis with fibrosis." (PMID 32908189, 2020). "Consistent with increased AHR and PEMT expression in steatosis patients, hepatic PC levels were modestly, but significantly, increased, and PE levels were decreased resulting in an increased ratio of PC/PE." (PMID 29416063, 2018). "AHR is identified to induce cellular oxidative stress and increase lipid peroxidation in NAFLD, and activation of AHR has pleotropic effects on steatosis of NAFLD." (PMID 29464180, 2017). "Furthermore, modulation of the expression and activity of CYP and steatosis-related nuclear receptors, such as PXR, AhR, and CAR, was observed in the mixtures and the formulated product." (PMID 40295322, 2025). "Many NR ligands have been linked specifically to steatosis, including LXR, PPARα, PPARγ, PXR, GR, FXR, CAR, ER, RAR, and AhR, yet AhR does not belong to the NR family." (PMID 38791241, 2024). "In a recent study, it was demonstrated that mice with the liver-specific overexpression of a constitutively active AhR (CA-AhR) developed spontaneous steatosis without inducing widespread hepatotoxicity." (PMID 38067179, 2023). "Furthermore, AhR, CYP1A1, and PPP2R2D expression in ALD patients increased with decreases in p-AMPKα as histological steatosis scores worsened." (PMID 36241614, 2022). "Collectively, these results suggest that AHR-mediated repression of Hmgcr and other genes involved in cholesterol biosynthesis may protect against TCDD-induced steatosis in mice." (PMID 31676775, 2019). "To determine if hepatic expression of PEMT and the PC/PE ratio are also aberrantly elevated in NAFLD steatosis patients, we measured mRNA levels of PEMT, AHR, and SHP in liver samples from 15 normal individuals, 15 simple steatosis patients, and 15 severe NASH-fibrosis patients." (PMID 29416063, 2018). "β-NF activated the AhR in both liver and thymus as evidenced by increased CYP1A4 mRNA expression, and, like TCDD, suppressed NAD+ levels in both liver and thymus and produced steatosis and thymic atrophy." (PMID 28536482, 2017). "The possibility that AhR may increase liver TG levels and promote steatosis in part through regulation of the 1C cycle genes has not been reported." (PMID 29416063, 2018).
gastric cancer (36 papers, 2009 to 2025). A primary or metastatic malignant neoplasm involving the stomach. "In this study, Aryl hydrocarbon receptor (AhR) expression was associated with lymph node and distant metastasis in patients with gastric cancer and was correlated with clinicolpathological pattern." (PMID 25226618, 2014). "Furthermore, the stomach expresses cytochrome P450 isoforms including CYP1A1 and significant associations between CYP1A1 polymorphisms and gastric cancer risk have been reported in humans, suggesting that the altered function of AhR-downstream molecule induces the stomach abnormality." (PMID 31226941, 2019). "AHR is highly expressed in gastric cancer tissues, and its signaling can be activated by various environmental pollutants, suggesting a potential role in esophageal inflammation and mucosal damage related to GERD." (PMID 41305834, 2025). "Previous research has demonstrated that excessive activation of AhR in mice exacerbates gastric cancer, suggesting a significant role for AhR in the pathogenesis of gastric cancer." (PMID 40136551, 2025). "Although previous study has demonstrated that AhR activation increased Mmp9 expression in gastric cancer cells, our study found that SCFAs supplementation promoted AhR activation and suppressed the expression of Mmp9 in EAE mice." (PMID 38976012, 2024). "Genetic depletion of AhR suppresses viability, proliferation, migration, and invasion of gastric cancer cells, and in vivo administration of the AhR inhibitor, biseugenol, prevents gastric tumor growth, metastasis, and peritoneal dissemination." (PMID 38807762, 2024). "The novel aryl hydrocarbon receptor inhibitor, Biseugenol, activates Calpain-10 and inhibits Aryl hydrocarbon receptor, thus inducing ER stress and obstructing gastric cancer peritoneal metastasis." (PMID 39247601, 2024). "AhR is strongly expressed and localized in the nucleus of human gastric cancer tissues and cell lines." (PMID 38807762, 2024). "Transgenic mice expressing a constitutively active dioxin/AhR mutant (CA-AhR) due to a deletion in the ligand-binding domain of AhR rapidly developed stomach cancers." (PMID 39200369, 2024). "Medical-related statistics have proved that compared with precancerous lesions, the expression of AHR in gastric cancer (GC) tissue is significantly increased." (PMID 36829212, 2023). "The results showed that taxifolin significantly inhibited the survival, proliferation, migration, invasion and tumor growth of gastric cancer through the aryl hydrocarbon receptor (AhR)/cytochrome P450 1A1 (CYP1A1) signaling pathway." (PMID 37261284, 2023). "Mice overexpressing an active AhR exhibit enhanced stomach cancer, suggesting a role of AhR in carcinogenesis." (PMID 35203450, 2022). "We also analysed a possible link between the immune checkpoint PD1/ PDL1, IDO1 and AhR expression in gastric cancers." (PMID 35203450, 2022). "Aza-PBHA increases PKCα phosphorylation and histone acetylation levels in human gastric-cancer cells by facilitating the interaction of HDAC with AhR." (PMID 33451095, 2021). "In terms of tumor progression and metastasis, AHR activation enhanced gastric cancer cell invasiveness, in part by induction of MMP-9 expression." (PMID 32907554, 2020). "We conclude that stomach cancers whose tumour cells express cytosolic AhR are likely to be sensitive to 5F 203 and that 5F 203 represents a putative novel therapeutic agent in treatment of certain gastric cancers." (PMID 31876059, 2020). "A decline in AhR protein levels and an increase in cytochrome P450 1A1 (CYP1A1) expression in a dose- and time-dependent manner observed after treatment with DIM demonstrate the correlation between AhR and gastric cancer." (PMID 27447608, 2016). "In this study, DIM inhibited gastric cancer cell growth mediated by aryl hydrocarbon receptor (AhR) pathway activation, resulting in G1-phase cell cycle arrest and apoptosis." (PMID 27447608, 2016).
gastric cancer (continued). "The high expression rate of the AhR was 67.5% (27/40) in gastric cancer case and low expression rate 32.5% (13/40) in neoplastic tissues." (PMID 25226618, 2014). "To investigate a possible role for AhR in gastric cancer progression, we performed immunohistochemical analysis of 40 patient's human gastric cancer specimens and demonstrated increase in AhR expression, as compared with benign tissue adjacent to the tumor." (PMID 25226618, 2014). "Our data presented here demonstrate that AhR pathway can be activated in gastric cancer AGS cells and AhR pathway activation in AGS cells induces MMP-9 expression and enhances AGS cells migration and invasion activity." (PMID 19371443, 2009). "In conclusion, the present study demonstrate that AhR pathway can be activated in gastric cancer AGS cells and AhR pathway activation induces MMP-9 expression and activity which ultimately contributes to AGS migration and invasion in vitro." (PMID 19371443, 2009). "Because degradation of ECM and basement membrane is an essential step in tumor invasion and metastasis, our results provide insight into the mechanism and function of the AhR pathway and its impact on these processes during gastric cancer progression." (PMID 19371443, 2009). "AhR pathway activation enhances gastric cancer cell invasiveness likely through a c-Jun-dependent induction of MMP-9." (PMID 19371443, 2009). "Our results provide insight into the mechanism and function of the AhR pathway and its impact on gastric cancer progression." (PMID 19371443, 2009). "In another of our studies, we found that AhR expression and nuclear translocation were significant higher in gastric cancer than in premalignant lesions and normal gastric mucosa." (PMID 19371443, 2009). "According to the recently described mechanism of 3D collagen-triggered CAR-T cell exhaustion, some inhibitors of the production of KynA or AHR pathway may increase the efficacy of CAR-T cell therapy toward gastric cancer." (PMID 39996879, 2025). "For example, it has been reported that the aryl hydrocarbon receptor and Helicobacter pylori can interact with the tryptophan metabolite kynurenine to weaken the immune system, increase the production of inflammatory cytokines, and induce gastric cancer." (PMID 39897929, 2025). "The results revealed that GPx2 expression impacted kynurenines (KYNU)-mediated metabolism, in addition to the involvement of the reactive oxygen species (ROS)-mediated KYNU-kyn-AhR signaling pathway in gastric cancer progression and metastasis following GPx2 knockdown." (PMID 39409942, 2024). "A pro-tumorigenic role for AhR has also been largely reported in gastric cancers." (PMID 38807762, 2024). "Also, MAPK signals activated the IDO1 level via the kynurenine/AhR perturbation loop pathway in gastric cancer." (PMID 35687267, 2023). "Therefore, in recent years, researchers have studied the activation of the AHR pathway in EBV-associated gastric cancer (EBVaGC) and EBV-negative gastric cancer (EBVnGC) cell lines to observe the effect of EBV infection on the AHR pathway in GC cells." (PMID 36829212, 2023). "Thus, the functional pathway of AHR is regulated leading to the promotion of gastric cancer development." (PMID 34784845, 2021). "In addition to being hyper-expressed in some malignant cells, the AHR was shown, as early as 2000, to be “constitutively active” in adult T cell leukemias and cancers of the stomach, liver, prostate, head and neck, breast, brain, and skin." (PMID 33396563, 2020). "Furthermore, transgenic mice that overexpress IL-1β developed gastric inflammation and gastric cancer, a response also found in transgenic mice expressing a constitutively active AhR." (PMID 31035533, 2019). "Furthermore, AhR expression and nuclear translocation were significantly increased in a severe phenotype, such as gastric cancer." (PMID 31226941, 2019).